CTSD (cathepsin D)
Diseases named in the same sentence as CTSD in open-access papers (continued):
Sharing a sentence is not in itself a finding about the gene and the disease.
tumor (continued). "It has been postulated that cathepsin D directly promotes tumor growth by degrading and remodeling the basement membrane and the stroma surrounding the tumor, and also acts indirectly by stimulating other enzymes or in conjunction with other cathepsins." (PMID 30177970, 2018). "IF IHC staining demonstrated the expression of both cathepsin B and cathepsin D by the OCT4− cells within the tumor nests and the OCT4+ CSC subpopulation within the peritumoral stroma." (PMID 30177970, 2018). "CTSD was shown to be overexpressed and secreted by several types of tumor cells including lung, breast and PCa." (PMID 28767721, 2017). "Several studies have found that cathepsin D affects various different steps in tumor progression and metastasis, including fibroblast outgrowth and tumor angiogenesis." (PMID 29375176, 2017). "In 87% of cases, the proteins belonged to pathways related to local tumor progression, metastasis and/or angiogenesis (i.e. cathepsin D, MMP-9, eNOS, Leptin, ANGPTL4, autotaxin)." (PMID 29245929, 2017). "It has been shown that cathepsin D expression level was higher in RCC tumor tissues and urine than benign or normal volunteer samples." (PMID 28586363, 2017). "Colorimetric in situ hybridization demonstrated the presence of mRNA transcripts coding for cathepsin B and cathepsin D within the tumor cells (pink, arrows) in the IDHWGB samples." (PMID 28611989, 2017). "The level of expression of cathepsin B and cathepsin D in GBM has been shown to have a positive correlation with tumor aggressiveness and cancer prognosis, inferring a crucial role for the proteins in the biology of IDHWGB." (PMID 28611989, 2017). "Previously, data have shown that cathepsin D is a critical contributor to many steps of tumor progression, including the stimulation of cancer cell proliferation, the inhibition of tumor apoptosis, and growth of micrometastasis." (PMID 29375176, 2017). "The diagnostic and prognostic significance of increased cathepsin B (CTSB) and cathepsin D (CTSD) concentration in the serum of cancer patients were evaluated for some tumor types." (PMID 26995190, 2016). "The presence of CTSB and CTSD in the serum of the patients with NPC correlated with the tumor node metastasis (TNM) scores (p = 0.001)." (PMID 26995190, 2016). "Increased levels of cathepsin D have been observed in cancer patients with other tumor entities as well." (PMID 26856534, 2016). "In this context, CTSD seems to play an essential role in the multiple step process of tumor progression, including the stimulation of cancer cell proliferation, growth of micrometastasis, and the inhibition of tumor apoptosis in several carcinomas." (PMID 26203049, 2015). "The role of CTSD in cancer has been postulated as promoting tumor growth directly by degrading and remodelling the basement membrane and the interstitial stroma surrounding the primary tumor." (PMID 26203049, 2015). "In a study limited to stage III tumors (n = 185), tumor cell cathepsin D expression was related to longer OS in univariate analysis, with no such role for stromal expression." (PMID 24860785, 2014). "We have identified that cathepsin D expression was significantly greater in cells from invasive front (IF) area and liver metastasis (LM) than those from main tumour body (MTB)." (PMID 22919486, 2012). "A role for cathepsin D in cancer metastasis was first demonstrated in an in vitro study using rat tumor cells in which overexpression of procathepsin D was associated with metastatic potential." (PMID 22919486, 2012). "The concentration of cathepsin D was found to be elevated in tumor cells at the IF area and LM compared to cells at the MTB in tissue from the same patients." (PMID 22919486, 2012).
tumor (continued). "S100P induces the expression of cathepsin D, an aspartyl protease, that takes part in the proteolytic degradation of the extracellular matrix, hence it increases the invasive potential of the tumor." (PMID 23166536, 2012). "On the one hand, cathepsin D expression in tumor and stromal cells at the IF region has been reported to significantly correlate with lymph node metastasis and hence survival." (PMID 22919486, 2012). "By so doing we identified that cathepsin D was expressed more strongly at the IF area in both tumor cells and what we identified to be macrophages surrounding tumor glands compared to its expression in the MTB." (PMID 22919486, 2012). "The gel spot position and concentration of cathepsin D in these three areas of tumor were validated with 2DE western blotting." (PMID 22919486, 2012). "Expression of cathepsin D in tumor cells at the IF and in LM was significantly higher than that in the MTB when profiled using 2 D-DIGE." (PMID 22919486, 2012). "Cathepsin-D has been reported to play an essential role in multiple tumor progression steps, affecting cell proliferation, angiogenesis, and apoptosis." (PMID 22506042, 2012). "Paradoxically strong expression of cathepsin D in the cells of the main tumor body was noted in late-stage disease and significantly correlated with distant metastasis and shorter cancer-specific survival." (PMID 22919486, 2012). "Animal and human data suggest that CTSD selectively degrades macrophage inflammatory proteins and is possibly used by tumor to escape antitumoral immune response." (PMID 21689475, 2011). "Given that stromal cathepsin D expression is observed in a broad spectrum of tumors, we addressed its possible functional implications on tumor cell behavior." (PMID 17183660, 2006). "For OS, PAI-1, cathepsin D, tumour size and ploidy were statistically significant in univariate, but PAI-1 was the only independently significant factor in Cox analysis (P < 0.001, RR 8.9)." (PMID 10408848, 1999). "Antigen levels of uPA, PAI-1 and cathepsin D were immunoenzymatically determined in tumour tissue extracts." (PMID 10408848, 1999). "bFGF levels did not correlate with other variables, including axillary nodes, hormone receptors, cathepsin D and the serum tumour markers CA15.3 and CEA." (PMID 9365172, 1997). "This is consistent with a model in which PEAR1 promotes tumor cell dormancy by binding CTSD." (PMID 41185039, 2025). "We therefore searched for other proteins interacting with the extracellular part of PEAR1, which may mediate the effect of PEAR1 on tumor cell dormancy, and identified CTSD." (PMID 41185039, 2025). "A recent explored the effect and molecular mechanisms of cathepsin D (Cat D) in the tumor microenvironment and showed that Cat D-mediated expression of CCL20 in cancer cells can promote polarization of M2 macrophages enhancing epithelial mesenchymal transition (EMT) and tumor metastasis." (PMID 39985603, 2025). "Addition of CTSD reverted the effects of CTSD knock-down in all tumor cells tested." (PMID 41185039, 2025). "How CTSD promotes tumor growth and inhibits tumor cell dormancy is still poorly understood." (PMID 41185039, 2025). "Moreover, in vitro experiments demonstrated that tumor-derived cathepsin D reduces CSTC activity in the tumor microenvironment through cathepsin D-mediated complexation and proteolysis." (PMID 38288036, 2024). "In addition, from this study, Cathepsin D lost its independent significance as prognostic factor (for BCSS) when HER2 expression is introduced in the multivariate analysis along with tumour grade, size and stage." (PMID 38578521, 2024). "This suggests that tamoxifen may increase Cathepsin D concentration in tumours that already express it, thereby altering the prognosis for this specific patient group." (PMID 38578521, 2024). "Additionally, it was found that Cathepsin-D expression is greatest in invasive areas, suggesting its involvement in tumor progression." (PMID 37108361, 2023).
tumor (continued). "As described in our study, the cathepsin D targeting system demonstrated successful binding to tumor cells in vitro, suggesting that it could similarly accumulate in the TME in vivo." (PMID 37896224, 2023). "Here, we present the development and evaluation of a new delivery system for tumor targeting based on immunoliposomes functionalized with pepstatin A—a natural peptide inhibitor of cathepsin D. A lipid tail was added to pepstatin A, enabling its incorporation into the liposomal lipid bilayer." (PMID 37896224, 2023). "Cathepsin D, a lysosomal protease, is another proteolytic enzyme elevated in tumor-bearing mice." (PMID 35326491, 2022). "On the other hand, overexpression of the CTSD gene, along with defective segregation in the acidic compartments, leads to abnormal secretion of the precursor proCD, which can be found in the culture media and body fluid of tumor bearers." (PMID 35563171, 2022). "Specifically, PDOs have lower levels of several factors (including B-cell lymphoma 2/Bcl-2, MMP2, Cathepsin D and Survivin) as compared to CTCDOs, suggesting that proteins related to tumor cell survival and aggressiveness increase during sequential stages of the disease." (PMID 35260172, 2022). "Patients with metastatic laryngeal SCC that demonstrate the presence of cathepsin D positive tumor cells are at a higher risk of cancer relapse than those without these tumor cells." (PMID 34621666, 2021). "HPA database showed that CTSD expression was significantly up-regulated in tumor tissues." (PMID 34552622, 2021). "It is found that APOE and CTSD play an essential role in many aspects of the tumor, such as cell adhesion, the effect of ROS, the regulation of oxidative stress, fat metabolism, and the regulation of tumor tissue." (PMID 34873574, 2021). "Continued exposure of CTSD-deficient tumor cells to nutrient restriction did not culminate in cell death, in contrast to neurons that already succumb to death by CTSD deficiency alone." (PMID 33046706, 2020). "To address the underlying mechanism, we generate tumor cell lines from mice with or without mammary epithelium-specific CTSD deficiency." (PMID 33046706, 2020). "By this approach, we are able to avoid the CLN10 neurodegeneration and to show a marked delay of tumorigenesis upon CTSD deletion in mammary epithelial cells, while CTSD deficiency in myeloid cells does not affect tumor progression." (PMID 33046706, 2020). "Moreover, the levels of mature-CTSB and mature-CTSD were decreased in tumor sample from high-dose treatment." (PMID 31186406, 2019). "In addition, in all cases analyzed, the stromal tissue of CRC was strongly stained for CTSD (red arrow), especially in the more invasive areas of the tumor tissue (blue line and red arrows)." (PMID 31497251, 2019). "Upregulation of cathepsin D has also been observed within GBM tumor cells." (PMID 28611989, 2017). "Based on our results, CTSD could therefore serve as a tumor marker for malignancies and metastasis of the bone." (PMID 26203049, 2015). "Involvement of cathepsin D in the stages of tumor progression in different cancer types." (PMID 26610586, 2015). "The level of cathepsin D, a lysosomal aspartyl protease, measured by immunoradiometric assay in OC tissue homogenates, was unrelated to clinical parameters or survival, with similar results for protein expression in tumor and stromal cells by IHC." (PMID 24860785, 2014). "Because the lymph node status, Cathepsin-D and Ki-67 index were factors strongly associated with outcome of TNBC patients, we built up a prognostic model based on the summation of points scored by the features of these three factors in tumor tissues." (PMID 24340082, 2013). "This implies that it is the protein-binding activity of cathepsin D that may be involved in stimulation of the tumor cells." (PMID 22439866, 2012).
tumor (continued). "Cathepsin D might be a good candidate as a target enzyme for prodrug activation because of its upregulation and redistribution to other cellular compartments in tumor cells and its substrate specificity." (PMID 22450679, 2012). "Interestingly, cathepsin D has been shown to stimulate fibroblast invasion and outgrowth and is reportedly involved in paracrine interactions between tumor epithelium and fibroblasts." (PMID 22291919, 2012). "In the discovery phase of our study cathepsin D was more highly expressed in LM and at the IF of CRC, relative to the MTB, suggesting it might be associated with tumor progression." (PMID 22919486, 2012). "Having identified that the cathepsin D staining at the IF could be in either tumor cells or macrophages, we scored the cathepsin D expression at the IF in our TMAs separately in the tumor cells and in the macrophages." (PMID 22919486, 2012). "Cathepsin D expression was examined at two cut-off levels (positive and highly positive) and separately identified within the epithelial and stromal component of all tumours." (PMID 9683294, 1998). "We conclude that pS2 could have a role in cathepsin D expression, and that it can be used in the assessment of a functioning oestrogen response machinery in those tumours that express only ER." (PMID 8123486, 1994). "Based on these observations, coupled with the relationship between LCN2/CTSD on tumor invasion progression, we speculated that the anti-invasive effect of LCN2 on GBM cell may be partly through CTSD expression and possibly involved in another molecular mechanism." (PMID 34062746, 2021). "Importantly, simultaneous cathepsin D expression was localized to the tumor parenchymal and stromal cells in 31.25% and 37.5% (respectively) and was understood as being a useful indicator for defining patient subgroups that showed variations in relapse-free survival." (PMID 33266503, 2020). "Experiments with constitutive CTSD knockout tumor cells support this hypothesis." (PMID 33046706, 2020). "However, the concrete molecular mechanisms of CTSD promoting PNI in SACC remains unclear, and further research is necessary to investigate the biology behaviors and underlying molecular mechanism of tumor cells at nerve invasion front in SACC." (PMID 30430081, 2018). "HIF-1α upregulates the levels of cathepsin D (CTSD), urokinase-type plasminogen-activator receptor (uPAR), and matrix metalloproteinase-2 (MMP2) enzymes, implicated in the basement membrane disruption leading intravasation and dissemination of circulating tumor cells (CTCs) in the organism." (PMID 28781970, 2017). "Therefore, we hypothesize that the FN1, CTSD, and GSN interaction is associated with cell adhesion and metastasis in tumor cells." (PMID 26056562, 2015). "Moreover, cathepsin D concentrations in pS2-rich tumours (pS2 above the median value, 5 ng mg-1 protein) were significantly higher (Mann-Whitney-Wilcoxon's rank-sum test: P = 0.00001) than those obtained in the samples expressing less than 5 ng of pS2 per mg of protein." (PMID 8123486, 1994). "Altogether, the aberrantly expressed signature genes (XRCC4, CTSL, CTSD, and HSPA8) is closely related to tumor malignant progression." (PMID 41399382, 2026). "Our identification of PEAR1 as a protein which efficiently binds CTSD and LOXL2 and thereby inhibits their pro-proliferative activity in the context of tumor cell dormancy also suggests PEAR1 as a tool to lower levels of free CTSD and LOXL2." (PMID 41185039, 2025).
tumor (continued). "We thereby identified PEAR1 as an endothelial transmembrane protein which promotes tumor cell dormancy in vitro and in vivo by binding and thereby inactivating the pro-proliferative proteins LOXL2 and CTSD." (PMID 41185039, 2025). "We found that PEAR1 induces tumor cell dormancy by binding lysyl oxidase like 2 (LOXL2) and cathepsin D (CTSD), which both inhibit tumor cell dormancy and promote tumor growth and metastasis." (PMID 41185039, 2025). "In conclusion, these results suggest that NDV infection triggers LMP in different tumor and avian cells, leading to the leakage of CTSB and CTSD from the lysosomal lumen to the cytoplasm." (PMID 38354122, 2024). "ProclarixTM is a novel tumor marker developed for csPCa detection that incorporates the serum measurements of thrombospondin 1 (THBS1), cathepsin D (CTSD), total PSA, and percent free PSA, along with age." (PMID 38392564, 2024). "Upregulated cathepsin activity (CTSB, CTSD, and CTSZ) and complement pathway (C1QA, C1S) indicated pro-tumor activity by the TAMs in this region." (PMID 38217035, 2024). "Cathepsin D is excreted into the TME, predominantly by tumor cells, where it can be activated and sustained due to the low pH in the TME." (PMID 37896224, 2023). "In order to confirm V8‐induced LMP in vivo, tumour tissue immunofluorescence showed LAMP1 and CTSD colocalization were decreased in 10 mg/kg group of V8 treatment." (PMID 36959764, 2023). "In contrast to CTSD and CTSB stimulating apoptosis, CTSS actually inhibits apoptosis and thereby promotes tumor progression." (PMID 36289617, 2022). "While intracellular CTSB and CTSD have been demonstrated to be pro-apoptotic, intracellular CTSS has been found to be anti-apoptotic in HCC (thus, tumor promoting)." (PMID 36289617, 2022). "Some studies have shown that Cathepsin D (CTSD) is a lysosomal aspartic protease, which can be used as a tumor marker." (PMID 34873574, 2021). "In addition, CTSD could regulate tumor tissue, cytochrome metabolic pathway, and oxidative stress." (PMID 34873574, 2021). "Among these cysteine proteinases, lysosomal CTSB, CTSD, CTSL, and CTSS have been shown to be involved in tumor malignant progression and are potential targets of anti-tumor therapy." (PMID 34923982, 2021). "Cathepsin D and both uPA and uPAR have been found highly expressed in PDAC and play a role in cell dissemination, which ultimately leads to tumour progression." (PMID 34439122, 2021). "Our previous studies showed that CTSB and CTSD are highly expressed in NPC metastatic tissues, and they increased cell motility and invasion, and promoted NPC tumor metastasis." (PMID 26995190, 2016). "Proteases, e.g. cathepsin D, uPA, MMP-11, are secreted by transformed or stromal cells of BC, and impact on tumor invasion and mestastasis." (PMID 27538498, 2016). "Gene expression analysis revealed a reduction in expression of the proteases Cathepsin D and MMP-2 in the OPG knockdown cells with reduced levels of MMP-2 maintained after primary tumor growth." (PMID 24976340, 2014). "We note that other proteases, including MMP-2 and cathepsin D, were also activated in an S2RPGRMC1-dependent manner, and cathepsin D plays a key role in tumor invasion and metastasis." (PMID 25594057, 2014). "The mechanism linking AGR2 to tumor invasion and metastasis is involved in several molecular alterations such as CTSB and CTSD." (PMID 24717913, 2014). "It is strongly detected in low-grade tumours (well-differentiated) with low (MIB1) growth fraction, but is independent of the tumour progression (size, node status, CD31, and cathepsin D)." (PMID 9252201, 1997).